CDK8 (cyclin dependent kinase 8)
Diseases named in the same sentence as CDK8 in open-access papers (continued):
Sharing a sentence is not in itself a finding about the gene and the disease.
breast carcinoma (continued). "While there is interest in the potential of CDK8 inhibitor development for colon cancer, CDK8 has also become a target of interest for acute myelogenous leukemia (AML), melanoma, prostate cancer, and breast cancer." (PMID 41596544, 2026). "Studies on CDK8 inhibitors for breast cancer have reported no change in ER expression, but prevented induction of ER-responsive genes by estrogen addition to estrogen-depleted cells." (PMID 41493967, 2026). "CDK8 activity has been successfully reduced by tools like small-molecule inhibitors (like Senexin A and B) and genetic techniques like shRNA or CRISPR/Cas9, demonstrating its potential as a therapeutic target in breast cancer." (PMID 40361480, 2025). "miR-26a-5p was also confirmed to inhibit breast cancer cell growth by suppression of RNF6 expression; miR-26b-5p played a suppressive role in inhibiting proliferation of breast cancer cells by negatively regulating CDK8." (PMID 35812757, 2022). "CDK8, CDK7, CDK4, and CDK1 predicted unfavorable outcomes in luminal A breast cancer patients." (PMID 35628286, 2022). "Conclusions were that CHD4 coactivates HIF to promote breast tumor growth, and that different mRNAs were also up-regulated in human breast tumors (ZMYND8, KDM4C (JMJD2C), CDK8, CREBBP (CBP), KAT), suggesting the heterogeneity of epigenetic regulation of HIF in breast cancer." (PMID 33981601, 2021). "Moreover, it has been shown that CDK8 contributes to epithelial-to-mesenchymal transition (EMT), a process which plays an important role in invasion and metastasis of breast cancer cells." (PMID 34689158, 2021). "Our results indicate that CDK7, CDK8, and CDK13 could be prognostic biomarkers for breast cancer patients." (PMID 33686962, 2021). "The function of CDK19 in breast cancer is not verified at present, but CDK8 acts downstream of the estrogen receptor as estrogen-induced transcription depends on CDK8 kinase activity." (PMID 31248103, 2019). "We have found that CDK8 inhibition by CDK8/19-selective small-molecule kinase inhibitors, by shRNA knockdown or by CRISPR/CAS9 knockout suppresses estrogen-induced transcription in ER-positive breast cancer cells; this effect was exerted downstream of ER." (PMID 28147342, 2017). "When CDK8 is present, breast cancer cells are not killed by NK cells and escape tumor surveillance." (PMID 34689158, 2021). "The contrast between the colon cancer cell lines and the breast cancer cell line results suggest that CDK8 may not be a major regulator of β–catenin in MDA-MB-468 cells, or a compensatory mechanism exists." (PMID 33291686, 2020). "In the context of estrogen receptor positive (ER+) breast cancer, it has been shown that CDK8 inhibition suppressed estrogen induced gene transcription through reduced RNAPII phosphorylation, suggesting a potential role of CDK8 inhibitors with antiestrogen therapy." (PMID 33291686, 2020). "We and others have previously shown that CDK8/19 is a negative prognostic marker in breast cancer." (PMID 28147342, 2017). "In the first Phase I clinical trial of a CDK8/19i, Senexin B (NCT03065010), the compound was well-tolerated in advanced breast cancer patients for up to eight months without adverse drug effects." (PMID 40149277, 2025). "The results showed that although the mRNA expression of CDK7, CDK8, CDK19, and CDK20 was higher in breast cancer tissues, none of these transcripts’ values reached statistical significance." (PMID 33686962, 2021). "Cyclin-dependent kinase 8 (CDK8), an oncogenic transcriptional regulator, and CDK19 are negative prognostic markers in breast cancer." (PMID 32765953, 2020).
breast carcinoma (continued). "Expression of CDK8, its paralog CDK19 and their binding partner Cyclin C are negative prognostic markers in breast cancer." (PMID 28147342, 2017). "Here, we have demonstrated that pharmacological inhibition of CDK8 in colon cancer cell lines HCT116 and Colo205 resulted in depletion of β–catenin protein while the same treatment of breast cancer cell line MDA-MB-468 did not appear to change β–catenin content." (PMID 33291686, 2020). "Although the inhibition of CDK8/CDK19 fails to induce apoptosis, synergistic effects in combinatorial therapies might be beneficial for breast cancer patients." (PMID 31248103, 2019).
colon carcinoma (44 papers, 2010 to 2026). "On one hand, CDK8 inhibition induces TIMP3 via SMAD-regulated upregulation of miR-181b, which constitutes the primary mechanism underlying the impact of CDK8 on the growth of liver metastases in colon cancer." (PMID 38606172, 2024). "CDK8, a serine/threonine protein kinase, is overexpressed in colorectal, breast, and hematological malignancies, and in colon cancer, high CDK8 levels are associated with poor clinical outcomes." (PMID 34771669, 2021). "Cdk8 overexpression has been associated with stimulating the Myc oncogene and its downstream targets in colon cancer." (PMID 30621145, 2019). "Overexpression of Cdk8 is associated with enhanced Wnt/β-catenin signaling in colon cancer." (PMID 31036676, 2019). "Similarly, CDK8 specific siRNA transfection down-regulated the expression of CDK8 in colon cancer cells, which was also associated with a decrease in the expression of β-catenin, inhibition of proliferation, increased apoptosis and G0/G1 cell cycle arrest." (PMID 22613733, 2012). "In the context of colon cancer cells, CDK8 antagonizes the E2F1 transcription factor’s ability to suppress β-catenin." (PMID 41596544, 2026). "By suppressing transcriptional reprogramming, CDK8/19 inhibitors (CDK8/19i) showed a unique ability to suppress the growth of metastases preferentially to primary tumors, as reported for colon cancer." (PMID 39541354, 2024). "Although SNX631 did not affect in vitro proliferation or in vivo primary tumor growth of murine 4T1 cells, CDK8/19i were previously shown to selectively affect the metastatic over the primary tumors in colon cancer." (PMID 39541354, 2024). "The proliferation of colon cancer cells that overexpress CDK8 can be effectively inhibited by knocking down CDK8, as reported in previous studies." (PMID 38606172, 2024). "Colon cancer cells were unable to proliferate and were arrested in the G0/G1 phase when CDK8 was knocked down." (PMID 38606172, 2024). "In colon cancer, CDK8 enhances the activity of β-catenin and suppresses the activity of E2F1 (repressor of β-catenin), thereby indirectly promoting the expression of c-myc." (PMID 37446017, 2023). "Chaga-derived ergosterol peroxide was shown to decrease the transcription of C- Myc, cyclin D1, and CDK-8 and ultimately reduced the growth of colonic tumors in mice." (PMID 37153767, 2023). "Although CDK8 inhibition exhibited weak antiproliferative activity in colon cancer cell lines, the CDK8/19 inhibitor Senexin B exerted a potent antitumor effect and augmented the effects of fulvestrant on ER-positive breast cancer." (PMID 33686962, 2021). "Collectively, all of the evidences pinpointed that the colon cancers with CDK8 amplification are more progressive with strong potential in distant migration toward the brain." (PMID 34795255, 2021). "The previous study has demonstrated the oncogenic role of CDK8 amplification in colon cancer cell proliferation as a positive mediator of β-catenin-driven transformation in the WNT pathway." (PMID 34795255, 2021). "Subsequent studies have further demonstrated that CDK8 phosphorylates Ser375 on E2F1 in colon cancer cells." (PMID 32961708, 2020). "Here, we observed different biological responses to CDK8 inhibition among colon cancer cell lines and the triple-negative breast cancer (TNBC) cell line MDA-MB-468." (PMID 33291686, 2020). "Cyclin-dependent kinase 8 (CDK8) is a positive regulator of the cell cycle and has been described as an oncogene in the context of chromosomal amplification in colon cancer cell lines." (PMID 33291686, 2020). "Amplification of 13q12 occurs in a significant fraction of colon cancer and CDK8 was identified by an RNA interference screen as a relevant gene target and likely oncogene." (PMID 33291686, 2020). "In the colon cancer cell lines, these results are consistent with the reported depletion of β–catenin due to CDK8 knockdown." (PMID 33291686, 2020).
colon carcinoma (continued). "It has been demonstrated that colon cancer cell lines treated with CDK8 RNAi result in decreased cellular levels of β–catenin." (PMID 33291686, 2020). "Other cancers with a relatively high frequency of gene amplification included GI cancers, among which colon cancers, in particular, showed a unique specificity of gene amplification for CDK8 over CDK19, in agreement with the original report." (PMID 31382571, 2019). "In order to more fully investigate the role of CDK8 in colon cancer, we aimed to develop a potent and selective small molecule inhibitor of CDK8." (PMID 31384837, 2019). "Nevertheless, small-molecule CDK8/19 inhibitors did show beneficial therapeutic effects in colon cancer models but these effects were observed only in vivo and specifically when targeting metastatic growth of colon cancers in the liver." (PMID 31382571, 2019). "In contrast, CDK8 was shown to suppress tumor growth in an in vivo model of APCMin colon cancer: the inducible deletion of CDK8 resulted in an increased tumor size and accelerated growth rates." (PMID 31248103, 2019). "CDK8 has been identified as an oncogene in colon cancer by regulating β-catenin activity via its kinase activity." (PMID 31552016, 2019). "Previous studies of human CDK8 have mostly focused on its potential as a therapeutic target in cancer, on the basis of the observation that amplifications of CDK8 are frequent in colon cancer." (PMID 30905399, 2019). "The role of CDK8 in both cellular signaling and colon cancer have relied upon RNAi mediated suppression of CDK8 and on the use of a kinase dead mutant CDK8." (PMID 31384837, 2019). "In colon cancer cells, CDK8 was recruited to the p21 locus upon transcriptional activation in a stimulus-specific manner." (PMID 30693281, 2018). "An integrated genomic analysis of colon cancer showed that CDK8, itself, is amplified in colorectal cancer and is important for mediating Wnt/β-catenin signaling in a subset of cancers where it is overexpressed or amplified." (PMID 30693281, 2018). "The molecular docking studies showed putative binding mode of the derivatives and their significant interactions with cyclin-dependent kinase-8 as prospective agents against colon cancer." (PMID 29274036, 2017). "The molecular docking studies of potent anticancer compounds 5l, 5k, 5i and 5p showed their putative binding mode and significant interactions with cyclin-dependent kinase-8 as prospective agents for treating colon cancer." (PMID 29274036, 2017). "While CDK19 is downregulated in leukemia, lymphoma and esophageal cancer, CDK8 is overexpressed and amplified in ~50% of colon cancers suggesting a selective role of CDK8 in this type of tumors." (PMID 25914884, 2015). "Some CDKs can be considered oncogenic, e.g., CDK4 in familial melanoma, CDK6 in MLL-rearranged leukemia, and CDK8 in colon cancer." (PMID 25914884, 2015). "Suppression of CDK8 expression inhibits the proliferation of colon cancer cells, which were originally characterised by their high level of CDK8 expression." (PMID 25635878, 2015). "Cdk8 exhibits copy-number gains in colon cancers, and recently it has been characterized as a coactivator of the beta-catenin pathway in colon cancer cell proliferation." (PMID 25180339, 2014). "Of the 47 colon tumors, the positive rate of CDK8 and β-catenin was 76.6% (36/47) and 95.7% (45/47)." (PMID 22104393, 2011). "To further confirm the expression of CDK8 and β-catenin in colon cancer, we detected the expression of CDK8 and β-catenin in fresh colon cancer tissues and adjacent normal tissues of the same patient." (PMID 22104393, 2011). "Neverthless, our observations suggested that CDK8-siRNA can effectively inhibit the transcription activity of the β-catenin signaling pathway in colon cancer cells HCT116, thereby resulting in the suppression of cell proliferation and promotion of apoptosis." (PMID 22104393, 2011).
colon carcinoma (continued). "As far as we know, studies on the role of CDK8 in the proliferation, apoptosis and cell cycle progression of colon cancer cells are still insufficient." (PMID 22104393, 2011). "CDK8 and β-catenin protein levels were also examined by real-time PCR and immunohistochemistry (IHC) in colon cancer tissues and adjacent normal tissues." (PMID 22104393, 2011). "Our observations demonstrated that the activity of CDK8 is essential to be able to regulate β-catenin-dependent transcription and transformation in colon cancer cells." (PMID 22104393, 2011). "In the present study, CDK8 specific interference was designed and transfected into a colon cancer cell line HCT116." (PMID 22104393, 2011). "The effect of small interfering RNA (siRNA) silencing of CDK8 on the growth of colon cancer cells was investigated." (PMID 22104393, 2011). "We also found out that CDK8 specific siRNA inhibited the proliferation of colon cancer cells, promoted their apoptosis and arrested these cells in the G0/G1 phase." (PMID 22104393, 2011). "In this study, we demonstrated that CDK8 specific siRNA transfection down-regulated the expression of CDK8, which is expressed in a high fraction in colon cancer." (PMID 22104393, 2011). "To verify whether overexpression of OXCT1 inhibits the migratory ability of colon cancer cells via CDK8, we treated the cells with the CDK8 inhibitor (MSC2530818)." (PMID 41492470, 2026). "In a significant fraction of colon cancers, the CDK8 gene is a target of chromosomal amplification." (PMID 41596544, 2026). "Knockdown of CDK8 in colon cancer cells with amplified CDK8 decreases proliferation." (PMID 41596544, 2026). "Notably, CDK8 has been identified as an oncogene and an enhancer of Wnt signaling, with its elevated level and activity promoting colon cancer cell proliferation." (PMID 40762106, 2025). "CDK8 is amplified in colon cancer, pancreatic cancer, and other cancer." (PMID 38606172, 2024). "Despite the diverse transcriptional resistance programs observed across tissue types, CDK8/19 inhibition completely prevented lung and colon cancer cells from developing resistance to ERK inhibition (bottom), and markedly delayed the emergence of resistance in pancreatic cancer cells." (PMID 38822082, 2024). "Of note, the expression of CDK8 can be regulated by the cell-adhesion protein Zyxin, a constituent of the focal adhesion complex which is involved in cellular motility, thereby promoting colon cancer cell proliferation." (PMID 38606172, 2024). "Similarly, lncRNA HAGLR targeting the miR-185-5p/CDK4/CDK8 axis promoted proliferation, migration, and invasion of colon cancer in vitro and in vivo." (PMID 35571488, 2022). "Furthermore, we used the clinical data of TCGA to show that the colon cancer patients with CDK8 amplification were diagnosed with more lymph node spread (p = 0.006, proportion test) and have significantly shorter DFS (p = 0.003, log-rank test)." (PMID 34795255, 2021). "In addition, CDK8 induced Mmp3 transcription in murine or MMP9 in human colon cancer cells through Wnt/β-catenin signaling pathway." (PMID 34067719, 2021). "Likewise, treatment of colon cancer cell line Colo205 with CDK8 inhibitor 4 results in a dramatic depletion of β–catenin protein." (PMID 33291686, 2020). "Knockdown of CDK8 in colon cancer cell lines led to decreased proliferation." (PMID 33291686, 2020). "It has been more than a decade since CDK8 was identified as an oncoprotein in colon cancer." (PMID 32961708, 2020). "Cyclin-dependent kinase 8 (CDK8) has been identified as a colon cancer oncogene." (PMID 33291686, 2020). "Cdk8 was firstly identified as oncogene in colon cancer by regulating β-catenin signaling." (PMID 31552016, 2019). "The Mediator kinase CDK8 and its paralog CDK19, together with their binding partner Cyclin C (CCNC), have been implicated through experimental studies in several malignancies, including cancers of the colon, breast, prostate, pancreas, melanoma, and leukemias." (PMID 31382571, 2019).